HIF1A (hypoxia inducible factor 1 subunit alpha)
Diseases named in the same sentence as HIF1A in open-access papers (continued):
Sharing a sentence is not in itself a finding about the gene and the disease.
tumor (continued). "The degenerating regions of the HeLaX-E9s showed crowding of the majority of the immune cells, and the tumor cells had nuclei with immunoreactive HIF-1α; additionally, there were spots in a few cells in the non-degenerating regions." (PMID 25874769, 2015). "When measured tumor ascorbate concentrations, rather than supplementation levels, were compared against HIF-1α, GLUT-1, CA-IX (from Western blot), and VEGF (from ELISA) protein levels, a strong and significant inverse association was detected." (PMID 25354695, 2015). "The use of ascorbic acid as a non-toxic adjuvant therapy to aid in the inhibition of HIF-1α activity in order to reduce tumor progression and improve patient response to clinical therapy warrants further investigation." (PMID 26547841, 2015). "HIF-1α expression was associated with the FIGO stage and histological type, but not with tumor size, lymph node metastasis, lymph-vascular involvement or microvessel density." (PMID 26622782, 2015). "We also found negative correlations between both 64Cu-ATSM and 18F-FDG with regard to the gene expression of CAIX (though non-significant) and HIF-1α in tumour." (PMID 26501874, 2015). "Importantly, tumor growth is strongly dependent on angiogenesis and in the tumor microenvironment, ROS generated by NADPH oxidases increase VEGF secretion in a HIF1α-dependent manner." (PMID 26584646, 2015). "Our results support the hypothesis that let-7 is a tumor suppressor that negatively regulates RAS, also in ES, and that HIF-1α may contribute to the aggressive metastatic behavior of ES." (PMID 26393682, 2015). "In the present study, we found that tumors of 2-DG fed mice had decreased levels of PI3K, phosphorylated Akt, and HIF-1α, which was in line with other studies showing down-regulation of PI3K/Akt signalling contributing to the anti-tumor effect of DER in murine tumor models." (PMID 26135741, 2015). "HIF-1α was also found to be inversely correlated with MIC gene expression, indicating that hypoxia was involved in the inhibition of NK cell reactivity toward tumor cells." (PMID 26441986, 2015). "Mechanistically, these hypoxic tumor responses are mainly mediated through the master regulator hypoxia-inducible factor-1 (HIF-1), a heterodimeric transcription factor consisting of oxygen-sensitive HIF-1α and constitutively expressed HIF-1β subunits." (PMID 25821081, 2015). "Based on this speculation, we detected the expressions of HIF-1α, COX2 and PEPCK in tumor tissue, and marked monocytes by F4/80." (PMID 25938544, 2015). "Indeed, although a single report has proposed a possible tumor-suppressor role for HIF-2α in HCC cells, hypoxia and HIFs (HIF-1α and HIF-2α) are currently seen as significant determinants of the progression of chronic liver diseases and HCC development." (PMID 25544768, 2015). "Nevertheless, the presence of HIF-1α seems likely to contribute to the aggressive tumor phenotype, regardless of the mechanism of its increased expression." (PMID 26046764, 2015). "All these results suggested that HIF-1α was not the unique factor affected by lactate in tumor microenvironment." (PMID 25938544, 2015). "The overexpression of HIF-1α has been confirmed in human tumors as compared with that in the respective normal tissues, and blocking HIF-1α activation significantly attenuates tumor growth, angiogenesis and progression." (PMID 26193287, 2015). "Inhibition of HIF-1α signaling by using RNAi or YC-1, a specific inhibitor of HIF-1α synthesis, both completely diminished mRNA level of VEGF and greatly inhibited endothelial cell proliferation promoted by HER2+ tumor cell-conditioned medium in both the absence and presence of HRG-β1 pretreatment." (PMID 26625311, 2015). "Furthermore, we demonstrated that Salirasib, a RAS inhibitor, significantly reduced HIF-1α and EWS-FLI-1 proteins and tumor growth in an ES mouse model." (PMID 26393682, 2015).
tumor (continued). "The result tells us that miR-20b maintains tumor cell growth through its regulation of HIF-1α and VEGF in normal condition." (PMID 26612965, 2015). "The hypoxia-Notch gene subset (HIF-1α/PGK1/VEGF/CA9/OPN-Notch1/Dll1/Hes1/Hes6/Hey1/Hey2) identified by us might hold prognostic implication and offer new opportunities in tumor sub-classification and targeted therapy." (PMID 25734817, 2015). "In the present study, the expression of HIF-1α, CA-IX, GLUT-1 and VEGF was examined in order to determine whether these molecules may be useful tissue biomarkers of tumor hypoxia." (PMID 26622782, 2015). "In contrast, stabilization of HIF-1α and HIF-2α in hypoxia leads to expression of genes involved in compensating physiological pathways such as angiogenesis, glucose utilization, cell proliferation, and tumor progression." (PMID 26205818, 2015). "Interestingly, their miRNA based therapy using synthetic let-7 supports our findings suggesting that increased levels of let-7 result in a reduction of HIF-1α and EWS-FLI-1, contributing to the reduction of tumor growth in-vivo." (PMID 26393682, 2015). "HIF-1, a heterodimeric complex composed of an O2-labile α-subunit (HIF-1α), which is degraded by the proteasome under aerobic conditions, and a stable β-subunit (HIF-1β), mediates the primary transcriptional response to hypoxic stress in tumor cells." (PMID 26416246, 2015). "Furthermore, shRNA-mediated targeting of HIF1α reduces survivin mRNA and protein expression in the SW480 colon cancer cell line, thereby increasing the apoptotic index and reducing in vivo tumor growth." (PMID 26584646, 2015). "HIF1α and TWIST are two important factors in the induction of tumor EMT and metastasis." (PMID 26196741, 2015). "Tumor burden and metastases increased with acetate supplementation for control or HIF-1α, but not ACSS2 or HIF-2α, knockdown." (PMID 25689462, 2015). "Besides HIF-1α expression, we also analyzed CA IX and GLUT1 expression by IHC, which are another hypoxia markers, to confirm the hypoxic condition of tumor." (PMID 26553068, 2015). "AECHL-1 could also downregulate HIF-1α expression and VEGF secretion under hypoxic conditions, thus reducing the fears of unnecessarily aggravating tumor metastasis as a result of anti-angiogenic therapy." (PMID 25952529, 2015). "It has been reported that HIF-1α preferentially induces genes in the glycolytic pathway and HIF-2α is involved in the regulation of genes important for tumor growth, cell cycle progression and maintaining stem cell pluripotency, including c-Myc and the stem cell factor OCT-3/4." (PMID 25726527, 2015). "Bearing in mind these observations, one may speculate that in poorly vascularized tumor regions, survivin-mediated VEGF synthesis and/or HIF1α mediated survivin and VEGF expression could promote vasculogenic mimicry and thus favor tumor survival." (PMID 26584646, 2015). "Further, we analyzed tumor samples from mice responding to Torin2 treatment and found reduced phospho-4E-BP1 staining, as well as reduced staining for survivin (reduced nuclear staining) and HIF-1α, a marker of aggressive cancer." (PMID 25945839, 2015). "HIF-1α, ROS and VEGF165 are three well-known biomarkers in tumor angiogenesis and tumor invasion." (PMID 25905434, 2015). "Expression analysis of tumor samples for key angiogenic and autophagy factors revealed that autophagy inhibition by CQ significantly potentiated the negative regulation of BA145 on VEGFR-2, HIF-1α, and HIF-1β, and increased pro-apototic signals." (PMID 25608686, 2015). "Similarly, administration of LMWF also inhibited the HIF-1α and VEGF expression in vivo, accompanied by a reduction of tumor growth." (PMID 26193287, 2015). "After we first observed a higher HIF-1α and CXCL8 expression in 102 HCC samples (as compared to matched adjacent non-tumor liver tissues), we additionally found a correlation between the expression level and tumor features." (PMID 26078356, 2015).
tumor (continued). "Re-expression of full-length wild-type HIF-1α in 786–0 cells has a negative effect on growth as tumor xenografts in mice." (PMID 26262842, 2015). "For example, HIF-1α induces the gene expression of various EMT regulators, including Twist, Snail, and Zeb1, thereby promoting a more aggressive tumor phenotype, which confers on cancer cells the ability to invade basement membranes and metastasize to distant sites." (PMID 25821081, 2015). "We found that the major factor of the tumor immunophenotype variation was characterized by a strong inverse relation between the expression of ER, PR, AR along with anti-apoptotic marker BCL2, on one side, and Ki67 and HIF-1α, on the other side." (PMID 26512778, 2015). "Considering the significant role of HIF-1α in angiogenesis in various types of cancer and the pathological angiogenesis biomarker, CD146, in tumor-derived angiogenesis, HIF-1α and CD146 immunostaining was performed to examine the expression of CD146 and HIF-1α in AdCC, PMA and NSG tissues." (PMID 25997612, 2015). "In addition, we have demonstrated that estrogenic GPER signalling activates HIF-1α/VEGF transduction pathway leading to angiogenesis and tumor growth." (PMID 26415222, 2015). "After hypoxia develops, HIF-1α and HIF-2α are generated by tumour cell activation." (PMID 25598425, 2015). "Altogether, these findings suggest that copper may trigger relevant biological actions through HIF-1α/GPER/VEGF transduction signalling in both cancer and endothelial cells toward angiogenesis and tumor progression." (PMID 26415222, 2015). "Regulation of HIF1α mainly occurs at the protein level, since it is degraded by the ubiquitin proteasome pathway (UPP) under normoxia conditions but is stabilized under hypoxia conditions in a tumor environment." (PMID 25896712, 2015). "Further analysis demonstrates that nicotine appears to increase HIF-1α (hypoxia-inducible factor 1, alpha subunit) expression in vivo with no change in a clinical marker of tumor hypoxia (immunohistochemical CAIX expression)." (PMID 26380225, 2015). "The expression of HIF-1α or CAIX did not correlate with the fraction of hypoxic tissue in any of the two tumor lines." (PMID 26502718, 2015). "HIF-1α stimulates transcription of multiple genes, including angiogenic vascular endothelial growth factor (VEGF), an important growth factor involved in tumor angiogenesis, and HIF-1α/VEGF pathway have been implicated in the development of multiple tumors." (PMID 25295523, 2014). "Since pVHL is present, other tumor suppressor activities are enabled, except for proteasomal degradation of HIF-1α due to the substrate being non-existent." (PMID 24886840, 2014). "This is seen in tumours that do not have known VHL mutations, and this represents a novel mechanism of HIF-1α accumulation." (PMID 24563687, 2014). "Though no significant change was observed in tumor weight of control and drug-treated mice tumors, Sac-1004 treatment did increase vascular perfusion and reduced HIF-1α expression." (PMID 24811731, 2014). "HIF-1α/VEGF axis, as a key regulator of tumor growth and metastasis, could be a promising drug target for RES in the development of an effective anticancer therapy for the prevention of hepatic tumor growth and metastasis." (PMID 25295523, 2014). "Therefore, to investigate the possible regulation of tumor angiogenesis by RBP2, we examined the expression of the transcription factors HIF-1α and VEGF in RBP2-overexpressing and -depleted NSCLC cells under normoxia at 36 hours after transfection." (PMID 25162518, 2014). "HIF-1α, VEGF, and BNIP3 were elevated in tumor samples (p < 0.01)." (PMID 24551593, 2014). "Tg-mediated increases in HIF-1α and HIF-2α in the tumor microenvironment were attenuated by 4-PBA." (PMID 25514597, 2014).
tumor (continued). "In the present study, we used the glucose analog 2-DG and the pharmacological Hsp90 inhibitor 17-AAG, which destabilizes the HIF-1α protein and disrupts STAT3-HIF-1α activation axis, to limit IMQ-induced aerobic glycolysis to enhance the anti-tumor activity of IMQ." (PMID 24658058, 2014). "Hypoxic fragments displayed more pronounced staining for HIF-1α than normoxic fragments, though the difference was significant only in stroma cells, not in tumor cells." (PMID 24460801, 2014). "Compared with HIF-1α, BAG3 shows a better correlation with tumor size." (PMID 24895585, 2014). "In addition, the bidirectional regulations between HIF-1α and COX-2 forming a positive feedback further promote tumor angiogenesis and tumor growth." (PMID 24413338, 2014). "Finally, the glycolytic inhibitor 2-DG and the Hsp90 inhibitor 17-AAG, which decreases HIF-1α protein stability, synergized with IMQ to induce apoptosis in tumor cells and effectively prevent tumor growth in mouse tumor xenograft models." (PMID 24658058, 2014). "Although Celastrol induced the transient accumulation of HIF-1α and VEGF, whether it can promote tumor angiogenesis and metastasis is a remaining question." (PMID 25383959, 2014). "Immunohistochemical staining for HIF1α was negative in epidermis overlying the tumour islands, while the HF showed weak scattered positive nuclear expression." (PMID 25181405, 2014). "HIF-1α stabilization in normoxia can be due to sustained activation of the mTOR pathway, which was previously shown to be responsible for regulating the translation of HIF-1α mRNA in other tumor types." (PMID 25166211, 2014). "These assays demonstrated that the abnormal expression of RANKL, HIF-1α, NRP-1 and VEGF proteins seen in clinical PCa tumor specimens could be easily detected in the isolated CTCs." (PMID 24551200, 2014). "Also, an increase in HIF-1α protein induced by hypoxia enhances transcription, expression, and secretion of S100A9 protein in the tumor microenvironment also by prostate cancer cells." (PMID 25193858, 2014). "Consequently, induced expression of HIF-1α downstream target genes, including GLUT-1, PDK1 and CAIX, provides survival advantages to tumor cells." (PMID 25420025, 2014). "Furthermore, crosstalk has been shown to exist between canonical Wnt signaling and HIF signaling in tumor progression and metastasis via the synergistic interaction of the Wnt target gene c-MYC with HIF-1α." (PMID 25396735, 2014). "In conclusion, Endostar combined with radiotherapy inhibits tumor cell proliferation and the expression of TGF-β1 and HIF-1α, which may affect the expression of VEGF and other genes." (PMID 24669250, 2014). "On the contrary, in our experimental set up WA decreased EMT-related components of the TGF-β signaling pathway (TGFA, TGFBR2, CDH11), as well as TGM2, HIF1A, several TNFSF family members and ANGPTL2, which stimulate tumor promoting pro-inflammatory responses and a hypoxic microenvironment." (PMID 24498382, 2014). "HIF-1-α induces the expression of different angiogenic growth factors, including vascular endothelial growth factor (VEGF) and platelet-derived growth factor (PDGF), acting on its respective receptors and promoting formation of new capillaries of tumor." (PMID 24744457, 2014). "Therefore, in tumor cells, where MYC levels are generally elevated, HIF-1α will only inhibit MYC activity during short periods of severe hypoxia, whereas, at other times, the high MYC levels can drive cellular proliferation." (PMID 25085992, 2014). "In contrast, HIF1α staining was only found in some cases with an expression in 10–90% of tumor cells (6/16 cases, 38%) but not in others (10/16 cases 62%)." (PMID 24498091, 2014). "Animal studies of metastatic breast cancer have demonstrated that lack of HIF-1α in malignant cells significantly reduced tumour progression and metastasis." (PMID 25128202, 2014).
tumor (continued). "Additionally, HIF-1α and HIF-2α drive angiogenesis during tumour development, whereas HIF-3α negatively regulates the HIF pathway in vascular cells by decreasing hypoxia-mediated VEGF expression." (PMID 24886719, 2014). "Furthermore, we measured the expression of HIF1α target genes involved in glycolysis, both in MIA PaCa-2 cells and orthotopic tumor tissues using western blotting and IHC analysis, respectively." (PMID 25103363, 2014). "Moreover, the glucose analog 2-DG and the Hsp90 inhibitor 17-AAG, which destabilizes the HIF-1α protein, synergized with IMQ to induce tumor cell apoptosis in vitro and significantly inhibited tumor growth in vivo." (PMID 24658058, 2014). "With the exception of Th17 cells, the role of HIF-1α in T cell subset differentiation within the tumor microenvironment has not been clearly defined in the literature and focused studies examining the role of HIF-1α on specific T cell subsets are warranted." (PMID 24904823, 2014). "Furthermore, miR-503, whose expression is down-regulated by hypoxia through HIF1α, also targets FGF2 and VEGFA for inhibiting tumor angiogenesis and growth." (PMID 24865854, 2014). "The interaction of HIF-1α and HIF-1β is critical in the process of tumor survival." (PMID 25068796, 2014). "Second, an effective statistical analysis of the patients with BAG3 high-/HIF-1α low- or BAG3 low-/HIF-1α high-expression in tumor is not available." (PMID 24895585, 2014). "The cooperation of PML-RARα with HIF-1α, and to a minor extent HIF-2α, is relevant to APL pathogenesis by impacting on a number of HIF-mediated functions, including spontaneous and chemokine-dependent cell migration, and tumor neo-angiogenesis." (PMID 24711541, 2014). "MRV infection again resulted in decreased HIF-1α levels in hypoxic tumor cells in the absence of MG132 at both times p.i. in all cell lines." (PMID 24504474, 2014). "Further investigation confirmed that PI3K/AKT/HIF-1α signaling activated by Gankyrin could promote Twist1, VEGF, and metalloproteinase 2 expression, and also promote EMT and motility/invasion of tumor cells." (PMID 24751719, 2014). "Interestingly, at the invasive front of CRCs, tumor cells displaying EMT are characterized by nuclear β-catenin as well as nuclear HIF1α." (PMID 24498091, 2014). "Thus, the combination of RNAi of HIF-1α and TAE had a marked synergistic effect on tumor growth inhibition." (PMID 25101278, 2014). "The variable expression of HIF-1α and CAIX within a tumor suggests that they may serve as valid biomarkers of intratumoral metabolic heterogeneity." (PMID 25127378, 2014). "Although it was described that gemcitabine did not affect tumour oxygenation or HIF-1α levels in HCT116 xenografts, it has also been reported that gemcitabine inhibited HIF-1α induction in A549 cells exposed to the hypoxia mimetic agent DFX." (PMID 25128202, 2014). "Because of HIF-1α's established role in promoting various hypoxia-driven prometastatic events (e.g., VEGF expression upregulation, angiogenesis, and tumor cell invasion), we next tested whether 15-LOX-1 modulates HIF-1α." (PMID 24634093, 2014). "Immunohistochemistry with RBP2 and HIF-1α antibodies showed a positive reaction in the nucleus, and VEGF antibodies showed a positive reaction in the cytoplasm of tumor cells." (PMID 25162518, 2014). "Hypoxia-inducible factor-1α (HIF-1α), is a basic helix-loop-helix transcription factor that regulates expression of VEGF and other genes that modulate growth, survival and metastasis of tumor cells under conditions of hypoxia." (PMID 23123638, 2013).